WEE1 (WEE1 G2 checkpoint kinase)
Diseases named in the same sentence as WEE1 in open-access papers (continued):
Sharing a sentence is not in itself a finding about the gene and the disease.
lung carcinoma (59 papers, 2008 to 2026). "Considering the strong synergistic effects of WEE1 kinase inhibitors with other downstream target inhibitors in KRAS-mutated lung cancer, we hypothesize that WEE1 inhibitors can also exert synergistic effects with KRAS G12C targeted inhibitors." (PMID 40885709, 2025). "To investigate whether the reduction in cell viability in lung cancer cells after the combined WEE1/ATR inhibitor treatment was associated with increased S-phase DNA damage, we performed flow cytometry analysis of γH2AX induction." (PMID 34359691, 2021). "In addition, five of the genes that we identified in this study, CPEB4, DUSP6, NF1, RNF4, and STAT2, were previously proposed as prognostic markers for NSCLC, whereas changes in the expression of MCM4 and WEE1 were associated with lung cancer development." (PMID 27418131, 2016). "Using the PGL4 WEE1 haplotype promoter luciferase reporter assay, we confirmed that WEE1 haplotype promoters can mediate allele-specific transcription of WEE1 in lung cancer cell lines H1299 and A549 after treatment with the DNA-damaging chemotherapy agents cisplatin and gemcitabine." (PMID 26057002, 2015). "Similar patterns occur in gefitinib-resistant lung cancer models, where WEE1 upregulation increases Tyr15 phosphorylation and promotes resistance." (PMID 41099621, 2026). "Gastrodin inhibits lung cancer cells resistant to pemetrexed by promoting survivin degradation through the inhibition of the Akt/WEE1/CDK1 signaling pathway." (PMID 39468027, 2024). "For example, miR-16 has been found to induce apoptosis and is downregulated by the WEE1 G2 checkpoint kinase in radioresistant lung cancer cells." (PMID 37629015, 2023). "The effect of DADS has also been reported to induce ROS in human colon cancer COLO 205 and A549 lung cancer cells through the upregulation of cyclin B, cdc25c-se-216-9, and Wee1." (PMID 35213970, 2022). "In recent studies, Wee1 inhibition has been shown as a promising therapeutic target in lung cancer, hepatic cancer, and multiple myeloma." (PMID 33932119, 2021). "In conclusion, we investigated the effects of WEE1 and ATR inhibitors, alone and in combination, on U2OS osteosarcoma cells and on a panel of four lung cancer cell lines with different sensitivities to the WEE1 inhibitor." (PMID 34359691, 2021). "Our results also demonstrated that Wee1 is downregulated by C/EBPβ via direct binding to the distal promoter and it is required for the G2/M cell cycle progression in lung cancer cells." (PMID 30754676, 2019). "Recently, dual targeting of PLK1 and WEE1 has been reported to elicit AZD1775’s single agent cytotoxicity in lung cancer." (PMID 29954437, 2018).
lung carcinoma (continued). "Among the three age-dependent markers, an increased relative expression of NF1 and WEE1 genes had a protective effect on subjects, whereas an increased relative expression of MDM2 gene was a risk factor for developing lung cancer." (PMID 27418131, 2016). "An increased relative expression of WEE1 gene decreased the odds of having lung cancer by 74% for younger men and by 93% for younger women." (PMID 27418131, 2016). "Altogether, inhibitors of ATR, Chk1, and Wee1 are emerging as new cancer treatment agents, likely to be useful in lung cancer treatment." (PMID 25774168, 2015). "Synergistic effects have also been reported between inhibitors of ATR/Chk1/Wee1 and conventional lung cancer treatments, such as gemcitabine, cisplatin, or radiation." (PMID 25774168, 2015). "In summary, miR-129 suppressed lung cancer cell proliferation by arresting cell cycle at G2/M phase through inactivation of CDK1 by Wee1, and reduced cell migration and invasion in lung cancer through controlling the protein levels of NF-κB and MMP-2." (PMID 26081366, 2015). "We therefore asked whether combined inhibition of ATR and WEE1 in the lung cancer cells would give a synergistic reduction in cell viability associated with induction of DNA damage in S-phase, such as was observed for U2OS cells." (PMID 34359691, 2021). "To explore the potential of combined ATR and WEE1 inhibition for lung cancer treatment, we used a panel of four lung cancer cell lines with previously identified large differences in sensitivity to the WEE1 inhibitor MK1775 (sensitive SW900 > H1975 > A549 > H460 resistant)." (PMID 34359691, 2021). "Whereas, synergy effect in the combination of ATR inhibitor and WEE1 inhibitor is found in both high CCNE1-expressing osteosarcoma cell line and low CCNE1-expressing lung cancer cell lines." (PMID 37087441, 2023). "In a recent investigation by Rødland and colleagues, administration of a Wee1 inhibitor led to augmented phosphorylation of Chk1 S317 and ATR expression in all lung cancer cells." (PMID 37296592, 2023). "To further evaluate this new exciting approach, we investigated the effects of combined ATR/WEE1 inhibition in U2OS osteosarcoma and four lung cancer cell lines." (PMID 34359691, 2021). "Effects of the WEE1 inhibitor MK1775 and ATR inhibitor VE822 were investigated in U2OS osteosarcoma cells and in four lung cancer cell lines, H460, A549, H1975, and SW900, with different sensitivities to the WEE1 inhibitor." (PMID 34359691, 2021). "Together, these results suggest that despite elevated replication initiation, the reduction in viability upon combined treatment with WEE1 and ATR inhibitors cannot simply be explained by an increased induction of S-phase DNA damage in the lung cancer cells." (PMID 34359691, 2021). "Nonetheless, our findings with WEE1 inhibitors and Sotorasib suggest WEE1 inhibitors may enhance the efficacy of KRAS-targeted therapies, improving clinical outcomes in KRAS-mutant lung cancer." (PMID 40885709, 2025). "Similarly, survival analyses for low WEE1 and high AATK expression indicate a higher survival probability in BRCA and lung cancer, HNSCC, and PDA." (PMID 35902728, 2022). "However, combined inhibition of WEE1 and ATR appeared to reduce cell viability to a different extent in the four lung cancer cell lines, showing more than additive effects in H460, H1975, and SW900, but little synergy in A549." (PMID 34359691, 2021). "The discovery of feedback loop mechanisms with cyclin dependent kinase 1 (CDK1) and wee1 like protein kinase (WEE1) or the discovery of microRNA (miRNA) target interactions in the development of lung cancer in non-smoking females, are examples of applications of systems biology." (PMID 29848999, 2018).
glioblastoma (57 papers, 2011 to 2026). The most malignant astrocytic tumor (WHO grade IV). "PRKCG and WEE1, when upregulated, are known to be good prognostic markers in Glioblastoma, while high mRNA levels of RBL2 are known to be associated with HPV+ head and neck tumors." (PMID 34796107, 2021). "Loss of CHK1 and WEE1 expression was also reported for HDACi treated glioblastoma cells." (PMID 33670166, 2021). "We have also found that LCS1269 triggered G2 cell cycle block associated with Wee1/Myt1 axis activation, the upregulation of transcription factor Forkhead Box M1 (FOXM1), and its target Polo Like Kinase 1 (PLK1) in human glioblastoma cell lines." (PMID 40649791, 2025). "Checkpoint abrogation, by the Wee1 kinase inhibitor adavosertib, induced glioblastoma cell lines and primary cells, DNA-damaged by UNC0379, to progress to mitosis where they died by mitotic catastrophe." (PMID 37758718, 2023). "Altogether, our results demonstrate that the SETD8 inhibitor UNC0379 synergizes with the Wee1 inhibitor adavosertib in inducing caspase-mediated cell death in mitosis also of primary glioblastoma cells." (PMID 37758718, 2023). "Few studies reported Wee1 inhibition in the particular case of CSCs inducing radio-sensitization in glioblastoma." (PMID 34639030, 2021). "High expression of Wee1 has been found in several cancer types including acute leukemia, rhabdomyosarcoma, glioblastoma, lung cancer, and head and neck squamous cell carcinoma." (PMID 31427973, 2019). "Of note, we find that WEE1, which was proposed as an anti-tumour target in glioblastoma and whose expression negatively correlates with patient survival, is up-regulated in angiogenic ECs." (PMID 27049916, 2016). "More recently an in silico analysis of a large data set of glioblastoma identified WEE1 as over expressed and a key regulator of mitotic catastrophe." (PMID 24661910, 2014). "Finally, we demonstrate the efficacy of SETD8+Wee1 targeted inhibition in a glioblastoma xenograft mouse model." (PMID 37758718, 2023). "Altogether, our results demonstrate that the SETD8 inhibitor UNC0379 synergizes with the Wee1 inhibitor adavosertib in pushing DNA-damaged glioblastoma cell lines into mitosis, where they die by the caspase-mediated, genome stability safeguarding, mitotic catastrophe mechanism." (PMID 37758718, 2023). "In addition, glioblastoma patients whose WEE1 expression is upregulated have a shorter survival rate." (PMID 36142793, 2022). "In their dataset, the highest Wee1 mRNA expression was measured in glioblastoma, followed by non-small-cell lung carcinoma, (non-)seminoma and colon carcinoma, whereas the other cancer types mostly showed moderate overexpression as compared to the relevant non-neoplastic control tissue." (PMID 34639030, 2021). "Furthermore, inhibition of ATR has been shown to cause depletion of chemoresistant and tumorigenic CD133+ colon cancer cells, and Wee1 inhibition radio-sensitized glioblastoma stem cells in vitro." (PMID 25774168, 2015). "Other kinases are found to be overexpressed in glioblastoma, including the kinase WEE1." (PMID 25256166, 2014). "Finally, the necessity for WEE1 in cell division has recently been described in primary fibroblasts, and its specific importance in human glioblastoma has been demonstrated thereby independently validating our computational findings." (PMID 21358821, 2011). "PI3K inhibition-related G2/M arrest has been documented in glioblastoma and gastrointestinal carcinoma cells and can be explained by the fact that several important proteins in the regulation of the G2/M cell cycle checkpoint (e.g. Chk1, Wee1) have been identified as targets of PI3K19,21,61–63." (PMID 33004905, 2020). "The expression of Wee1 was in fact higher in CD133+ compared to CD133– primary glioblastoma cells, and Wee1 was among the most downregulated genes upon differentiation of PTEN positive glioblastoma stem cells, indicating that high levels of Wee1 may be required to maintain a stemlike state." (PMID 25774168, 2015).
glioblastoma (continued). "LINC00470 plays an oncogenic role in glioblastoma multiforme (GBM)-derived exosome by binding to miR-580-3p, regulating the levels of WEE1 and activating the PI3K/AKT/mTOR pathway." (PMID 36338993, 2022). "WEE1 was over expressed in all three high-grade tumors examined including medulloblastoma (medullo), primitive neuroectodermal tumor (PNET) and glioblastoma multiforme (GBM)." (PMID 24661910, 2014). "WEE1 was decreased in HEK293T cells and both glioblastoma cell lines." (PMID 35902728, 2022). "Moreover, we have previously identified LCS1269 as a potential anti-glioblastoma agent, probably interfering with cell cycle regulation through both direct CDK1 inhibition and indirect modulation of CDK1 activity through Wee1/Myt1 and FOXM1/Plk1 signaling pathways." (PMID 40649791, 2025). "Thus, to more efficaciously target glioblastoma, we reasoned that combining the SETD8 inhibitor UNC0379 with the Wee1 inhibitor adavosertib could be a successful strategy." (PMID 37758718, 2023). "However, another report found no radio-sensitization by the Wee1 inhibitor MK1775 in glioblastoma neural stem cells." (PMID 25774168, 2015). "Interestingly, Debio-0123 is in clinical trials in combination with standard treatment regimens, including radiotherapy for glioblastoma (GBM) patients (NCT05765812), as preclinical evidence has demonstrated its enhanced ability to cross the blood–brain barrier compared to previous Wee1 inhibitors." (PMID 39272874, 2024).
prostate carcinoma (49 papers, 2006 to 2025). A carcinoma that arises from epithelial cells of the prostate gland. "CHK1 inhibition synergized with WEE1 inhibition by blocking WEE1 inhibitor-induced feedback activation of CHK1 in prostate cancer cells." (PMID 37987002, 2023). "Our mechanistic studies suggest that Bcl‐xL, Bim, CHK1, c‐Myc, Mcl‐1, RRM1, RRM2 and Wee1 play a role in the antitumour activity of CUDC‐907 against prostate cancer." (PMID 32459381, 2020). "Down‐regulation of CHK1 and Wee1 would decrease the ability of prostate cancer cells to repair damaged DNA, leading to accumulation of endogenous damaged DNA, resulting in cell death if not repaired." (PMID 32459381, 2020). "A recent study found upregulation of BCL2 and WEE1 kinase in small cell neuroendocrine (SCN) cancers, and combining Navitoclax and the WEE1 inhibitor AZ-1775 was synergistic against SCN prostate cancer patient-derived xenografts." (PMID 32572160, 2020). "In our study, MLN4924 caused accumulation of WEE1/p21/p27, CDT1/ORC1 and NOXA/BIK, which were associated with MLN4924-IR-enhanced G2 cell-cycle arrest, DNA damage and apoptosis in prostate cancer cells." (PMID 27224919, 2016). "Combination regimens involving SETD2 inhibitors with WEE1 inhibitors, HDMIs, or PARPis have demonstrated encouraging therapeutic efficacy in preclinical cancer models and are expected to form the basis for new treatment strategies for prostate cancer." (PMID 40959108, 2025). "In prostate cancer, SOX2 dysregulates the cell cycle via upregulating WEE1 and CDK1, resulting in the insensitivity of prostate cancer to NHRSI." (PMID 38331879, 2024). "Taken together, our study provided compelling preclinical evidence for translating WEE1 and CHK1 inhibitors and their combination for treatment of castration-resistant lethal prostate cancers." (PMID 37987002, 2023). "Overall, these data provide a rationale for targeting WEE1 and CHK1 in advanced stages of prostate cancer, with CHK1 being more strongly indicated." (PMID 37987002, 2023). "We further demonstrated the efficacy and tolerability of the WEE1 inhibitor AZD1775 and CHK1 inhibitor SRA737 as single agents and in combination for CRPC/NEPC treatment in a transgenic mouse model of advanced prostate cancer." (PMID 37987002, 2023). "Taken together, the inhibition of WEE1 or CHK1 effectively suppresses the growth and metastasis of NEPC prostate tumors, supporting their values as single agents for prostate cancer treatment." (PMID 37987002, 2023). "To assess the potential therapeutic value of targeting WEE1 and CHK1 in prostate cancer, we first evaluated WEE1 and CHK1 expression in a panel of prostate cancer cell lines with different genetic backgrounds." (PMID 37987002, 2023). "Our functional studies provide direct evidence that CUDC‐907 induces DNA damage and apoptosis in prostate cancer cells at least partially through down‐regulation of CHK1, Wee1, RRM1 and RRM2." (PMID 32459381, 2020). "Overexpression of hPer1 inhibits cell proliferation and reduces the expression of Cyclin B1 and WEE1 proteins, promotes apoptosis, and inhibits cell proliferation in HCT116 human colonic cancer cells and in human prostate cancer cells." (PMID 31130878, 2019). "Western blot analyses confirmed that miR-890 transfection also reduced the predicted target genes WEE1, XPC and KU80 in LNCaP prostate cancer cells." (PMID 25845598, 2015). "As FZD6 knockdown downregulated WEE1, we reasoned that FZD6 knockdown may sensitize prostate cancer cells to WEE1 inhibitors." (PMID 41286306, 2025).
prostate carcinoma (continued). "Our real‐time RT‐PCR analyses revealed that CUDC‐907 treatment significantly decreased the transcript levels for CHK1, Wee1, RRM1 and RRM2 in prostate cancer cells, indicating a potential transcriptional mechanism responsible for the down‐regulation of these proteins by the agent." (PMID 32459381, 2020). "We also examined additional cell lines for WEE1 expression and sensitivity to WEE1 targeting, with prostate carcinoma cell lines PC3 and DU145, and the non-tumourigenic breast epithelial cell line MCF10A." (PMID 19357772, 2009). "Collectively, these data demonstrate a strong synergy of AZD1775 and SRA737 combination in 2D CRPC and NEPC cell cultures and 3D tumor spheroids, suggesting that the combined inhibition of WEE1 and CHK1 may be an effective treatment for advanced prostate cancer." (PMID 37987002, 2023). "Combinations of WEE1 and CHK1 inhibitors have not been investigated in any prostate cancer model, although there were a few reports of this combination in other cancer models." (PMID 37987002, 2023). "The WEE1 inhibitor AZD1775 and the CHK1 inhibitor SRA737 are in clinical trials for various cancers, but have not been examined in prostate cancer, particularly castration-resistant (CRPC) and neuroendocrine prostate cancers (NEPC)." (PMID 37987002, 2023).